CDKN1B (cyclin dependent kinase inhibitor 1B)
Diseases named in the same sentence as CDKN1B in open-access papers (continued):
Sharing a sentence is not in itself a finding about the gene and the disease.
tumor (continued). "Genes with Lasso regression coefficients |β| > 10 include LETMD1, a known oncogene, the known tumor suppressor CDKN1B, as well as several other genes whose variants have been linked with other cancers, such as RSPO3." (PMID 27124395, 2016). "In conclusion, CDKN1B V109G polymorphism seems to play a role in the development of aggressive tumours in MEN1." (PMID 25824098, 2015). "Although CDKN1B is considered to be a tumor suppressor gene, somatic loss-of-function mutations in this gene have rarely been detected in different cancers." (PMID 25416039, 2015). "p27Kip1 (encoded by the CDKN1B gene) is a member of the Cip/Kip family of cyclin-dependent kinase inhibitors (CKI) which have well-described nuclear-associated tumour suppressor functions in causing G1 cell-cycle phase arrest." (PMID 25003467, 2014). "Nonetheless, there have been suggestions that p27Kip1 is an ‘unconventional’ tumour suppressor as mutations affecting the CDKN1B gene are rare in human cancers." (PMID 25121353, 2014). "CDKN1B is a tumor-suppressor gene, and it encodes the protein with the same name." (PMID 39194755, 2024). "Genomic analysis showed that CDKN1B is associated with tumor progression." (PMID 35832790, 2022). "Loss of heterozygosity (LOH) is a characteristic of tumor suppressor genes but is rarely found in I-NETs with CDKN1B mutations, although it should be noted that CDKN1B appears to be a haploinsufficient tumor suppressor in other tumor types and in mouse studies." (PMID 34680217, 2021). "Studies of Cdkn1b‐deficient mice indicated that p27 is haplo‐insufficient for tumour suppression." (PMID 30549261, 2019). "In accordance with previous publications, we observed LOH in a minority of the samples available for investigation, further substantiating that factors besides that of the CDKN1B mutation may be involved in tumor development in patients with MEN4." (PMID 30990521, 2019). "In this study, we assessed whether the CDKN1B V109G polymorphism was associated with the development of aggressive tumours in 55 consecutive patients affected by MEN1." (PMID 25824098, 2015). "MEN1-related aggressive tumours or other malignancies were more frequent in participants with the CDKN1B genetic variant (8/24 patients in group A versus 5/31 in group B; 33.3 versus 16.1%), although this test did not result in statistical significance (P = NS)." (PMID 25824098, 2015). "The aim of this study was to verify whether the CDKN1B V109G polymorphism is linked to aggressive tumours in MEN1 patients." (PMID 25824098, 2015). "In conclusion, we provide the first evidence that among patients who develop MEN1-related tumours, those bearing the CDKN1B V109G polymorphism have a higher frequency to develop aggressive tumours and hence a more aggressive behaviour, emphasizing the added value of this variant." (PMID 25824098, 2015). "The CDKN1B V109G polymorphism could in part explain this characteristic, as it positively correlates with the onset of aggressive tumours." (PMID 25824098, 2015). "Interestingly, we and others identified CDKN1B germline mutations in patients with a MEN type 1 (MEN1)-like features, thereby establishing a direct link between p27 alterations and tumor predisposition also in humans (MEN4; OMIM # 610755)." (PMID 20492666, 2010). "Following this discovery, we identified a germline heterozygous nonsense mutation at codon 76 (c.692G>A, p.W76X) of the human CDKN1B gene in several members of a family with a variant of the MEN1 syndrome, thereby demonstrating that CDKN1B is a tumor susceptibility gene also in humans." (PMID 20824794, 2010).
tumor (continued). "Finally, we must consider that, despite the wide variety of neoplasms associated with CDKN1B, the true oncogenic risk in CDKN1B-mutated carriers is still unknown." (PMID 35355569, 2022). "In line with this knowledge, from the thorough study of CDKN1B mutation in human cancer we can readily appreciate that p27 is infrequently affected by inactivating mutations or loss of heterozygosity, which are events commonly affecting other tumor suppressors, such as p16ink4 and RB." (PMID 30976290, 2019). "Thus, the polymorphism may play a role in dictating the evolution of the malignancy whereby MEN1 acts as a ‘driver’ gene and the CDKN1B polymorphism as a ‘modifier’ of tumour progression." (PMID 25824098, 2015). "Moreover, since germline CDKN1B mutations have been found in patients, studies of the molecular phenotype of the rat mutation may broaden our understanding of the role of p27 in tumor predisposition in humans as well." (PMID 20492666, 2010). "Losses in tumor suppressor genes such as RB1 and CDKN1B further highlight the genomic instability of this tumor." (PMID 39925800, 2025). "In fact, CDKN1B, also known as cyclin‐dependent kinase inhibitor 1B, acts as a critical regulator of cell cycle progression, primarily functioning as a tumor suppressor by inhibiting cyclin‐dependent kinases (CDKs) and arresting cells in the G1 phase." (PMID 40658092, 2025). "Upregulated in PCa. miR-222-3p inhibits CDKN1B/p27; miR-517c-3p associated with higher Ca, PTH, tumor weight." (PMID 41210508, 2025). "PCa patients were divided into two cohorts: CDKN1B high expression (n = 20) and CDKN1B low expression (n = 18), based on the mean CDKN1B IHC scores in tumor tissues." (PMID 38997648, 2024). "Exposure to Eo33-EV, but not to Eo5-EV, up-regulated cyclin-dependent kinase inhibitor (CDKI) protein-related genes in tumor cells, specifically Cdkn1b and Cdkn2b in B16 cells and Cdkn2b and Cdkn1a in TC1 cells." (PMID 39061080, 2024). "CDKN1B, also known as p27, is a well-stablished tumor suppressor that plays a crucial role in cell proliferation by inhibiting cyclin-dependent activity." (PMID 38443798, 2024). "In contrast, CDKN1B and CDKN1C are cyclin-dependent kinase (CDK) inhibitors, p27Kip1 and p57Kip2 respectively, that usually act as tumor suppressors, but their regulation is altered during tumor processes, leading to unchecked cellular proliferation." (PMID 39336170, 2024). "We also observed an increase in dormancy markers NR2F1 and CDKN1B and a slowing of proliferation and tumor growth in vivo with GRHL2 overexpression." (PMID 39199676, 2024). "This analysis revealed a statistical relationship between CDKN1B expression and various tumor characteristics, including clinical prognosis, cell infiltration, and gene mutation." (PMID 37432583, 2023). "The CDKN1B expression levels in tumor patients was further validated using immunohistochemistry (IHC) and quantitative real-time PCR." (PMID 37432583, 2023). "The fingerprint fp160 composed of three clinical parameters: Gleason primary score, tumor stage, psa, and two molecular protein expression levels for CDKN1B and NF2 has emerged as very concise and performant." (PMID 37188913, 2023). "CDKN1B mutations are responsible for MEN4 syndrome, which causes a MEN1-like phenotype with other related tumours." (PMID 37810884, 2023). "Due to the crucial role of CDKN1B in tumor progression, a pan-cancer analysis of the link between CDKN1B and diverse tumor types is critical for cancer therapy." (PMID 37432583, 2023). "The tumor suppressor PTEN is connected to WNT/CDKN1B signaling via regulation of the PI3K/AKT pathway and is also involved in morphogenesis and growth arrest by interacting with CDH1." (PMID 37313172, 2023).
tumor (continued). "FOXO‐1, FOXO‐3, and FOXO‐4 are partially redundant tumor suppressors that induce pro‐apoptotic genes such as TRAIL and cell cycle inhibitors such as cyclin‐dependent kinase inhibitor 1B (CDKN1B; encoding p27) in some settings." (PMID 37584250, 2023). "This relationship assisted in clarifying CDKN1B’s function in oncogenesis from the perspective of clinical tumor tissues and provided a potential therapeutic target for treating human cancers." (PMID 37432583, 2023). "Tumor suppressive and anti-metastatic activities of CDKN1B are achieved via its inhibition of cell cycle progression." (PMID 35397647, 2022). "The expression of miR-222 was significantly up-regulated in the muscle tumor tissues, while the expression levels of two target genes of miR-222, cyclin-dependent kinase inhibitor 1B (CDKN1B) and CDKN1C, were down-regulated in the tumors." (PMID 36497250, 2022). "CDKN1B protein is thought to be a tumor suppressor with a haploid phenotype, and CDK2 activity is increased in the absence of p27." (PMID 35126159, 2022). "CDKN1B was the most significant gene in both analyses (Padj = 6.3 × 10−12, patient-level data; Padj = 1.5 × 10−11, tumor-level data)." (PMID 35922826, 2022). "Like CDKN1B, TNRC6B was identified as one of the genes showing statistical evidence of positive selection for mutations in SI-NETs, suggesting a candidate tumor suppressor role for this gene in a subset of tumors." (PMID 35922826, 2022). "It has been shown that miR-200b stimulates tumour growth by targeting and negatively regulating CDKN1B, a negative regulator of the cell cycle, in TGFBR2-null CRC cell lines." (PMID 36140249, 2022). "Studies have shown that M2-sEVs transfer miRNA-221-3p to tumor cells to target CDKN1B, promote cell proliferation and G1/S conversion, and promote the progression of EOC." (PMID 35832790, 2022). "Because miR-221-3p directly suppresses the cyclin-dependent kinase inhibitor 1B (CDKN1B), these exosomes can resolve the cell cycle arrest in the G1/S and help tumor cells proliferate." (PMID 35550636, 2022). "CDKN1B encodes p27Kip1, a CDK inhibitor that prevents cell cycle progression from G1 to S phase, thus acting as a tumor suppressor gene." (PMID 34638668, 2021). "miR-221 targets key tumor suppressors, including CDKN1B/p27, CDKN1C/p57, PTEN, TIMP3, and DNA damage-inducible transcript 4 (DDIT4)." (PMID 33572780, 2021). "Clinically, CDKN1B downregulation is correlated with poor prognosis and the more aggressive tumor phenotype of HNSCC." (PMID 33718274, 2021). "CDKN1A/p21 and CDKN1B/p27 are members of a family of cyclin-dependent kinase inhibitors that act as tumor suppressors and inhibit cell proliferation." (PMID 34095224, 2021). "Given the dysregulation of CDKN1B in various cancers, the knowledge of the direct regulation of CDKN1B by PATZ1 provides a promising perspective in tackling tumor development and progression." (PMID 33598459, 2021). "In samples with high B7‐H3 expression, recurrent alterations included the deletion of short arm of chromosome 12 (12p), which contains tumor suppressors such as CDKN1B, ETV6, DUSP16, and miR‐613." (PMID 34562306, 2021). "Our previous results indicated that MIAT competitively inhibited miR-150-5p, which in turn stimulated CDKN1B expression and eventually mediated its anti-tumor function." (PMID 32549789, 2020). "The Cip/Kip family members, CDKN1A and CDKN1B, can arrest cell proliferation and were initially considered as tumor suppressors." (PMID 32899752, 2020). "The tumor tissues were then collected for WB analysis, and the results indicated that the expression levels of CDKN1B in the ID8‐miR‐221‐3p‐OE group and the ID8‐WT + M2 exos group were significantly lower." (PMID 32590883, 2020).
tumor (continued). "Cyclin dependent kinase inhibitor 1B (CDKN1B) was an important regulator of cell cycle progression and tumor suppressor in variety of human malignancies." (PMID 32549789, 2020). "Down-regulation of the miR-200 family at the invasive front in comparison to the central part of tumour was observed as well as a correlation of expression of miR-200b, CDKN1B, ONECUT2 and ZEB2 expression to nodal metastases." (PMID 31623346, 2019). "It is known to act as a tumor-suppressor in PCa and suppression of CDKN1B leads to growth promotion of PCa cells." (PMID 31562322, 2019). "In cancer studies where bromodomain and HDAC inhibitors have been studied most, both mechanisms have been shown to increase the expression of cdkn1b and txnip in tumor cells to induce cell cycle arrest." (PMID 31043677, 2019). "Second, the works on SI-NET confirm once again that CDKN1B acts as haploinsufficient tumor-suppressor, as already observed in different mouse models." (PMID 30065701, 2018). "Potential tumor suppressor miR-218-5p strongly regulates the CDKN1B, which is responsible for cell cycle progression control." (PMID 30200635, 2018). "The strongest prognostic power (P = 0.0024 and 0.00065) came from the gene-set pair of two ENSC markers (CDK2 and CDKN344) with two NB tumour suppressors (CDKN1B and CDKN2D45, 46)." (PMID 28246384, 2017). "The EMT inhibitor miR-200b was shown to stimulate tumor growth in TGFBR2-null CRC by targeting CDKN1B and negatively regulating p27/kip1." (PMID 26863633, 2016). "The complete loss of P27 protein according to immunohistochemistry in these LOH-positive tumors indicates that CDKN1B behaves as a classical tumor suppressor gene." (PMID 25416039, 2015). "Ches1, Tcf3, Ccnc and Gfi1 are transcriptional repressors, Pten and Runx3 are tumor suppressors, and Cdkn1b is a cell cycle inhibitor." (PMID 24859236, 2014). "These include caveolin 1 [which directly binds DLC1 and contributes to its tumor suppressive roles], CDKN1B [which is an inhibitor of and directly binds to CDK6], and cyclin D1 [which forms a complex with CDK6]." (PMID 25425654, 2014). "The p27Kip1 protein, encoded by the CDKN1B gene, is a member of the Cip/Kip family of CDK-binding cell cycle inhibitors, and is well known for its tumor suppressor function." (PMID 23440295, 2013). "In mice, Cdkn1b acts as a tumor suppressor due to its cyclin-CDK regulatory function and it acts as an oncogene through a cyclin-CDK-independent function." (PMID 23236518, 2012). "From the results of the microarray analysis, we selected 5 genes i.e., K-ras, c-MYC, DNMT1, Tpd52, CDKN1b for PCR confirmation because they are already considered as tumor-related genes." (PMID 22206623, 2011). "In contrast, CDKN1B overexpression inhibited tumor development accelerated by FAM84B." (PMID 38997648, 2024). "In these instances, it appears that though CDKN1B is present in the tumor, it is not acting as a driver mutation and is not necessary for metastasis." (PMID 38123518, 2024). "Loss of mitosis in tumor cells is associated with a marked reduction in cyclin-dependent kinase (CDK1) transcription and/or loss of its active form (CDK1-P-Thr 161), which coincides with upregulation of CDKN1A, CDKN1B, and CDKN1C." (PMID 39766809, 2024). "This evidence suggests that CDKN1B does not act as a classic tumor suppressor gene following Knudson’s ‘two-mutation’ criterion and that the down-regulation of p27Kip1 protein likely occurs at a post-transcriptional and/or post-translational level." (PMID 39519139, 2024).
tumor (continued). "Therefore, the regulation of CDKN1B has an impact on tumor cells due to its relationship with the cell cycle." (PMID 37432583, 2023). "Therefore, in contrast to MEN1 syndrome, haploinsufficiency for CDKN1B appears to be enough for tumours to occur in MEN4 syndrome." (PMID 36334246, 2023). "Therefore, CDKN1B protein is frequently degraded as a substrate for ubiquitination to promote tumor cell proliferation." (PMID 36792756, 2023). "In addition to the previously reported CDKN1B loss-of-function mutations, we observed potential loss-of-function gene alterations in TNRC6B, a candidate tumor suppressor gene in a small subset of ileal NETs." (PMID 35922826, 2022). "CDKN1B is a target of miR-200b, which is believed to have a tumor-promoting role in CRC." (PMID 34046357, 2021). "In addition, mutations in CDKN1B and NTRK3 genes have been recently found associated with this tumor." (PMID 34804623, 2021). "TMIGD1 inhibits tumor cell proliferation and cell cycle arrest at the G2/M phase through regulating expression of p21CIP1 (cyclin-dependent kinase inhibitor 1), and p27KIP1 (cyclin-dependent kinase inhibitor 1B)." (PMID 34503512, 2021). "P21 (CDKN1A) and P27 (CDKN1B) are known as negative regulators that could induce cell cycle arrest at the G1/S phase and block tumor cell growth." (PMID 34869591, 2021). "Germline mutations occur in several known genes (AIP, PRKAR1A, GPR101, GNAS, MEN1, CDKN1B, SDHx, MAX) as well as familial cases with currently unknown genes, while somatic mutations in GNAS are present in up to 40% of tumours." (PMID 33805450, 2021). "miR-455-5p may exert tumor promoting roles by inhibiting the expression of CDKN1B and influencing cell cycle and miR-1255a may be oncogenic by down-regulating SMAD4 and affecting TGF-β signaling pathway, which resulted in poor prognosis." (PMID 34707990, 2021). "Additionally, hemizygous deletions encompassing CDKN1B that suggest a role for p27 as a tumor suppressor in small intestine neuroendocrine tumors have been identified." (PMID 32590883, 2020). "The expression status of MIAT-miR-150-5p-CDKN1B signal axis was further characterized in xenograft tumor at both transcriptional and translational levels, which consolidated our in vitro observations and supported the physiological role of MIAT as ceRNA for miR-150-5p." (PMID 32549789, 2020). "Correlating with this, genetic crosses of Cdkn1b+/- and Cdkn1b-/- mice with mammary (MMTV-neu) and prostate (Nkx3.1and Pten deficient) tumor models also demonstrated a dosage sensitive effects as Cdkn1b+/- crosses increased tumorigenesis, while complete deletion of p27 decreased it." (PMID 30893315, 2019). "However, in the CGC tumour tissues, the genes most frequently showing CNGs were CDKN1B (42.9%), H3F3A (23.8%), CDK2 (14.3%), NFKBIA (14.3%), and VEGFA (14.3%)." (PMID 30989433, 2019). "RASSF1A inactivation may alter the cell cycle in both tumor types, whereas hypermethylation of CDKN2A and inhibition of CDKN1B and CDKN2C caused by MEN1 loss are characteristic of PanNETs." (PMID 30657883, 2019). "Interestingly, for the first time this work reported the discovery of biallelic inactivation of CDKN1B, a feature very commonly found in recessive tumor suppressor genes." (PMID 30065701, 2018).